PGC (progastricsin)
Description:
Hydrolyzes a variety of proteins.
Synonyms: PEPC; PGII
Tractability: Small molecule: it has a high-quality binding pocket; it belongs to a druggable protein family. Antibody: UniProt places it where antibodies can reach, with medium confidence; UniProt predicts a signal peptide or a membrane-spanning region; its Gene Ontology location is reachable by antibodies, with medium confidence. PROTAC: a small molecule that binds it is known.
Target class: Aspartic protease; Aspartic protease A1A subfamily; Protease; Enzyme; Aspartic protease AA clan
Gene: Protein-coding gene on chromosome 6 (41,736,711 to 41,754,109, reverse strand). Ensembl gene ENSG00000096088.
Subcellular location: Secreted
Subcellular location (Human Protein Atlas): Nucleoplasm; Predicted to be secreted
Gene Ontology:
Molecular function: aspartic-type endopeptidase activity
Biological process: positive regulation of antibacterial peptide production; digestion; proteolysis
Cellular component: extracellular region
Genetic constraint (gnomAD): Loss-of-function variants: 30 observed, 41.07 expected, observed/expected ratio (o/e) 0.73, 90% interval 0.55 to 0.99. The upper end of that interval is the gene's LOEUF score, 0.99, which puts it in group 4 of 6, group 1 being the genes least tolerant of losing a copy. Missense variants: 437 observed, 459.92 expected, observed/expected ratio (o/e) 0.95, 90% interval 0.88 to 1.03. Synonymous variants: 170 observed, 189.38 expected, observed/expected ratio (o/e) 0.9, 90% interval 0.79 to 1.02.
Homologues: Orthologues: chimpanzee PGC (99% identical), macaque PGC (97% identical), pig PGC (84% identical), rat Pgc (74% identical), mouse Pgc (74% identical), guinea pig PGC (72% identical), tropical clawed frog MGC108380 (69% identical), tropical clawed frog pgc.2 (69% identical), Drosophila melanogaster Bace (41% identical), Drosophila melanogaster CG17134 (38% identical), Drosophila melanogaster CG33128 (38% identical), Drosophila melanogaster CG6508 (37% identical), and 10 more. Paralogues in human: PGA3 (50% identical), PGA4 (50% identical), PGA5 (50% identical), CTSE (47% identical), CTSD (40% identical), NAPSA (37% identical), REN (33% identical), BACE2 (31% identical), BACE1 (28% identical).
Diseases named in the same sentence as PGC in open-access papers:
PGC is named in the same sentence as 85 diseases in open-access papers, as found by Europe PMC text mining. Sharing a sentence is not in itself a finding about the gene and the disease. The quoted sentences say what the papers report.
gastric cancer (28 papers, 2008 to 2025). A primary or metastatic malignant neoplasm involving the stomach. "Taking these findings together, we conclude that PGC loss is the result of gastric carcinogenesis and acts as a protective factor for chemical induction of gastric cancer." (PMID 37291517, 2023). "PGC protein expression was negatively linked to lymph node metastasis, dedifferentiation, and low Her-2 expression of gastric cancer (p < 0.05)." (PMID 37291517, 2023). "We aimed to explore the associations of polymorphisms in three microRNAs (miRNAs) (let-7e rs8111742, miR-365b rs121224 and miR-4795 rs1002765) that target PGC with the risk and prognosis of gastric cancer/atrophic gastritis." (PMID 28067243, 2017). "We found associations between PGC rs3789210 CG/GG genotypes and reduced gastric cancer risk and between PGC rs6939861 A variant allele and increased risks of both gastric cancer and atrophic gastritis." (PMID 25551587, 2014). "We previously identified the associations of three tagSNPs (rs4711690, rs9471643 and rs6458238 polymorphisms) in PGC gene with risk of atrophic gastritis or gastric cancer." (PMID 25551587, 2014). "The interaction of pri-let-7a-1 rs10739971 and PGC polymorphisms in the risk of gastric cancer/atrophic gastritisa." (PMID 24586594, 2014). "Our findings highlight an important role of PGC rs3789210 and rs6939861 in altering susceptibility to atrophic gastritis and/or gastric cancer." (PMID 25551587, 2014). "We newly found associations between PGC rs3789210 CG/GG genotypes and reduced risk of gastric cancer and between PGC rs6939861 A variant allele and increased risks of both atrophic gastritis and gastric cancer." (PMID 25551587, 2014). "Nevertheless, once infected by H. pylori, the subject carrying PGC rs6912200 variant genotypes has an increased risk of suffering from gastric cancer." (PMID 25551587, 2014). "This study highlights an important role of PGC genetic variations in the susceptibility to gastric cancer." (PMID 25551587, 2014). "As for the PGC SNP, in addition to PGC rs4711690, rs6458238 and rs9471643 identified previously, our study newly found rs3789210 in intron 3 and rs6939861 in 3′ downstream of PGC gene had main effects on susceptibility to gastric cancer." (PMID 25551587, 2014). "Many researchers have found it plays a key role in gastric cancer and the PGC polymorphism could serve as one of the diagnosis biomarkers for GC." (PMID 28232943, 2017). "As the three described polymorphisms of let-7e, miR-4795 and miR-365b are all located in the important promoter regions, we speculate that these miRNA SNPs may be associated with the downregulation of PGC expression, thus increasing gastric cancer risk." (PMID 28067243, 2017). "The phenomenon of an effect modification by H. pylori infection observed in the PTPN11 and PGC interaction may provide an important hint to help prevent gastric cancer by eradicating H. pylori in susceptible people." (PMID 26158864, 2015). "Taking together, this study found for the first time that PGC rs3789210 was associated with a reduced risk of atrophic gastritis and PGC rs6939861 was associated with increased risks of both atrophic gastritis and gastric cancer." (PMID 25551587, 2014). "Moreover, PGC rs6912200 CT/TT genotypes had a positive interaction with H. pylori infection in conferring an increased risk of gastric cancer, and individuals carrying such genotypes had lower levels of histological and serum PGC protein expression." (PMID 25551587, 2014). "In the present study, we found that PGC expression was negatively linked to aggressive features, including dedifferentiation, depth of invasion, lymph node metastasis, and short survival of gastric cancer, indicating that PGC loss might be a useful marker of progression and a favorable prognosis." (PMID 37291517, 2023).
gastric cancer (continued). "However, the roles of the other five tagSNPs (rs6941539, rs6912200, rs3789210, rs6939861 and rs2040017) of PGC gene in susceptibility to gastric cancer remain unknown, which requires further clarification." (PMID 25551587, 2014). "Research has demonstrated the potential of PGC in gastric cancer screening and prevention, making the PGC-IQGAP1 interaction a potential research direction for improving gastric cancer prognosis." (PMID 41035668, 2025). "Circulating progastricsin concentrations are elevated in some stomach disorders, including Helicobacter pylori gastritis and colorectal and gastric cancer." (PMID 39300663, 2024). "The Kaplan–Meier plot indicated a positive relationship between PGC mRNA expression and overall survival in gastric cancer patients with T2, T3, N1 + 2 + 3, N1, N2, N3, M0, or IV stage, diffuse subtype, or Her-2-positive disease (p < 0.05, data not shown)." (PMID 37291517, 2023). "PGC expression suppressed the proliferation, anti-apoptosis, migration and invasion of gastric cancer cells possibly by interaction with CCNT1, CNDP2 and CTSB." (PMID 37291517, 2023). "We found lower mRNA expression of PGC in gastric cancer than in normal mucosa in both the xiantao and UALCAN databases (both p < 0.05)." (PMID 37291517, 2023). "PGC expression was found to suppress the proliferation, anti-apoptosis, migration and invasion of gastric cancer cells, but versa for PGC knockdown in gastric epithelial cells." (PMID 37291517, 2023). "PGC downregulation was seen in gastric cancer, but PGC deletion resulted in resistance to chemically-induced gastric carcinogenesis." (PMID 37291517, 2023). "PGC mRNA level was inversely correlated with the T and G stage and a short survival of gastric cancer (p < 0.05)." (PMID 37291517, 2023). "According to TCGA, PGC mRNA expression was inversely correlated with the T and G stage of gastric cancers (p < 0.05)." (PMID 37291517, 2023). "The expression of PGC was weaker in gastric cancer than in normal mucosa at both mRNA and protein levels according to bioinformatics analysis and immunostaining, respectively." (PMID 37247123, 2023). "Several other studies focused on the miRNAs targeting PGC and their relationship with gastric cancer." (PMID 34093839, 2021). "Our research group previously found encoding gene PGC polymorphisms could affect the susceptibility to atrophic gastritis (AG) and gastric cancer (GC)." (PMID 30155999, 2018). "For PGC rs4711690 and IL1B rs1143623, rs4711690 GG/GC genotypes were associated with a reduced risk of gastric cancer and atrophic gastritis, but only in the presence of GC/CC genotypes at rs1143623." (PMID 26158864, 2015). "Individual genetic effects of 13 single nucleotide polymorphisms (SNPs) in PGC, PTPN11, TLR4, and IL1B on the susceptibility to gastric cancer and atrophic gastritis have been reported in our previous studies." (PMID 26158864, 2015). "In this study, we found new SNP interactions among H. pylori-related host genes PGC, PTPN11, and IL1B modifying the susceptibility to atrophic gastritis and gastric cancer." (PMID 26158864, 2015). "In our previous studies, we found that the genotype frequencies of five tagSNPs of PGC (rs4711690, rs6458238, rs9471643, rs3789210, and rs6939861) in gastric cancer and/or atrophic gastritis were significantly different from those in controls." (PMID 26158864, 2015). "Sequenom MassARRAY platform method was used to detect polymorphisms of pri-let-7a-1 rs10739971 G→A, PGC rs4711690 C→G, PGC rs6458238 G→A, PGC rs9471643 G→C, and ERCC6 rs1917799 in 471 gastric cancer patients, 645 atrophic gastritis patients and 717 controls." (PMID 24586594, 2014). "Serum PGC protein levels were detected by ELISA in a total of 1850 subjects consisting of 832 controls, 737 atrophic gastritis and 281 gastric cancer patients." (PMID 25551587, 2014).
gastric cancer (continued). "We found that miRNA polymorphism and PGC and ERCC6 polymorphisms showed strong statistical association with gastric cancer or atrophic gastritis." (PMID 24586594, 2014). "The association between co-function of PGC, MUC1 and MUC2 and the occurrence and development of gastric cancer and precancerous disease needs to be clarified in the future." (PMID 23937908, 2013). "Of particular interest is that PGC has been proposed as an indicator of gastric cancer, and the serum level of PGC was used as a biomarker for precancerous lesions of the stomach." (PMID 21060876, 2010). "In our research, we found PGC may act as a tumor suppressor in the development and metastasis of gastric cancer." (PMID 38791874, 2024). "However, in the dynamic cascade process from normal gastric mucosa to superficial gastritis, chronic atrophic gastritis, intestinal metaplasia, dysplasia, and finally to gastric cancer (GC), PGC expression level is successively decreased." (PMID 38791874, 2024). "PGC was mainly expressed in gastric cancer, colorectal cancer, and liver cancer cell lines." (PMID 33067881, 2020). "Furthermore, we detected the mRNA expression of PGC in gastric cancer cell lines including SGC7901, BGC823, AGS, and MKN45 and human immortalized gastric epithelial cell line (GES‐1) by quantitative real time PCR." (PMID 29963765, 2018). "In addition, the expression of PGC was far lower in gastric cancer tissues than that of corresponding normal tissue by western blot." (PMID 29963765, 2018). "Pepsinogen C (encoded by PGC) is the mature form of an aspartic proteinase present in the gastric mucosa and serum, and is used in a serological test for early screening of gastric cancer and precancerous disease." (PMID 28067243, 2017). "In summary, we observed novel SNP interactions among PGC, PTPN11, and IL1B which modified the risks of gastric cancer and atrophic gastritis and we provided important hints of effect modification by H. pylori infection on the cumulative effect of PGC rs6912200, PGC rs4711690, and PTPN11 rs12229892." (PMID 26158864, 2015). "Moreover, PGC rs6941539 CT and CT/TT genotypes had decreased expression levels of PGC protein in gastric cancer patients (P = 0.007 and 0.014, respectively)." (PMID 25551587, 2014). "The aim of this study was to investigate the interaction effects of pri-let-7a-1 rs10739971 with pepsinogen C (PGC) and excision repair cross complementing group 6 (ERCC6) gene polymorphisms and its association with the risks of gastric cancer and atrophic gastritis." (PMID 24586594, 2014). "Our findings indicate a further research direction for PGC genetic variation in gastric carcinogenesis, and also provide an important clue for personalized H. pylori management in the overall strategy to reduce the high prevalence of gastric cancer." (PMID 25551587, 2014). "There were joint effects of PGC rs6941539-rs6912200-rs3789210-rs6939861 loci, demonstrating genetic roles of TTCA, TTGG and CTCA haplotypes in altering susceptibility to atrophic gastritis and/or gastric cancer." (PMID 25551587, 2014). "Thus, we analyzed the interaction effect of pri-let-7a-1 rs10739971 polymorphism and PGC and ERCC6 polymorphisms, and its associations, with the risks of gastric cancer and atrophic gastritis." (PMID 24586594, 2014). "Thus, PGC has the potential to be a new therapeutic target for gastric cancer." (PMID 38791874, 2024). "Therefore, we speculated that the partner proteins of PGC might be involved in the regulation of aggressiveness of gastric cancer cells, such as proliferation and metastasis." (PMID 37291517, 2023). "The expression level of PGC in gastric mucosa is clearly decreased upon the development of gastric cancer (GC)." (PMID 34093839, 2021). "Hence, in addition to the PGC genetic variations, the interaction of PGC tagSNP with H. pylori infection is also a key component of gastric cancer susceptibility that should not be overlooked." (PMID 25551587, 2014).
gastric cancer (continued). "PGC can downregulate its interacting protein IQGAP1 and inhibit the Rho-GTPase pathway, thereby participating in the inhibition of gastric cancer cell migration and invasion." (PMID 38791874, 2024). "Firstly, we screened PGC protein expression in gastric cancer or epithelial cells by Western blot, and selected AGS for PGC overexpression and GES-1 for PGC knockdown." (PMID 37291517, 2023). "The top 10 marker genes shown here, such as TFF1 and PGC, are correlated to the gastric mucosal barrier and cellular protection, and the expression of TFF1 was indicated to be reduced in some gastric cancer patients, particularly in some precancerous lesions, such as atypical hyperplasia." (PMID 39044041, 2024). "In the paper, the authors demonstrated that PGC is a comparatively ideal negative marker of gastric cancer." (PMID 34149811, 2021). "As a negative marker, PGC has demonstrated important value in the screening, diagnosis, and prognosis of gastric cancer." (PMID 29963765, 2018). "The in situ expression of PGC in gastric mucosa is decreased considerably in the process of superficial gastritis → atrophic gastritis → gastric cancer (GC), proving that PGC is a comparatively ideal negative marker of GC." (PMID 28546787, 2017). "For PGC rs6912200 and PTPN11 rs12229892, TC/TT genotypes at rs6912200 and GA/AA genotypes at rs12229892 each conferred a reduced risk of gastric cancer and atrophic gastritis, but not if they were present together." (PMID 26158864, 2015). "Moreover, H. pylori infection status affected the ORs of three tagSNPs (PGC rs4711690, PGC rs6912200, and PTPN11 rs12229892) for the development of gastric cancer or atrophic gastritis." (PMID 26158864, 2015). "On the basis of the findings in the present study, it is reasonable to suggest that let-7a may participate in the processes of PGC inducing atrophic gastritis and ERCC6 inducing gastric cancer." (PMID 24586594, 2014). "To directly demonstrate the functional role of PGC genes in cellular invasion, we performed siRNA experiments where five PGC genes (p53CSV, MAP3K11, MTCH2, CPSF6, SKIP) were silenced in poorly-metastatic AGS gastric cancer cells." (PMID 18636107, 2008). "Furthermore, our western blot results confirmed that the expression of PGC significantly decreased and even absent in GC tissues; the same tendency was found in different gastric cancer cell lines by qPCR and western blot." (PMID 29963765, 2018). "One study found an interaction between pepsinogen (PGC) and IQGAP1, with a significant negative correlation between their expressions in gastric cancer cells." (PMID 41035668, 2025). "The in situ expression of PGC in the gastric mucosa is decreased considerably or even absent in the dynamic process of superficial gastritis (SG) → atrophic gastritis (AG) → gastric cancer (GC), showing that PGC is a comparatively ideal negative marker of GC." (PMID 28546787, 2017). "We performed Quantitative Real-time PCR (qPCR) on 6 up-regulated genes (COL1A, BGN, SPP1, MELK, IGFBP4, SPARC) and 4 down-regulated genes (PGC, SST, MT1X, S100P) to verify our data in gastric cancer tissues (Tumor) and noncancerous tissues (Normal)." (PMID 25928635, 2015).